AR (androgen receptor)
Diseases named in the same sentence as AR in open-access papers (continued):
Sharing a sentence is not in itself a finding about the gene and the disease.
tumor (continued). "Li Lingyan used the water extract of AR to observe the inhibitory effect of the drug on the tumor of mice after inoculation with H22, indicating that the water extract of AR can significantly inhibit the growth of H22 transplanted tumor in mice." (PMID 34887934, 2021). "Alterations in the transcriptional activity of estrogen receptors (ER) and androgen receptors (AR), coupled with tumor heterogenicity, are factors implied in endocrine therapy resistance." (PMID 33669559, 2021). "The prevalence of AR+ expressing tumours is generally ranging from 10% to 41% in TNBC cases, with rare reports showing rates up to 79%." (PMID 35047068, 2021). "A combination of this treatment showed inhibition of tumour cell growth and the induction of apoptosis, whilst also reducing recruitment of the AR to target gene promoter regions." (PMID 33993099, 2021). "The F133L alteration suggests an AR-dependent tumor, consistent with the patient’s prolonged clinical response to standard ADT." (PMID 33568750, 2021). "PCAL7 depletion via antisense oligonucleotides (ASOs) markedly suppressed AR signaling and tumor growth." (PMID 33219721, 2021). "Our understanding of AR-signaling in early hepatocarcinogenesis—where its tumour-inhibiting outcomes are maximized in HCC animal models—remain poorly understood." (PMID 33574348, 2021). "In our cohorts, both normal and tumor tissues of pRCC patients revealed higher expression of AR-FL than did normal and tumor tissues of ccRCC patients." (PMID 34440475, 2021). "For example, we previously found that proliferation of MCF-7 depends on AR signal, and the AR antagonist enzalutamide (Enza) inhibits tumor growth of MCF7 xenografts." (PMID 34736512, 2021). "A rising serum PSA level, which is an AR-dependent gene product, is often an indicator of tumor recurrence in individuals following ADT." (PMID 35582006, 2021). "To determine if AR regulation of the EWSR1 gene is through direct binding, we analyzed published AR ChIP-seq datasets from patient tumor samples and matched adjacent normal tissue." (PMID 34409300, 2021). "Of note, it has been observed that injecting astemizole in CRPC mouse xenografts significantly represses interaction of EZH2 with AR and inhibits tumor growth." (PMID 33810413, 2021). "In the current study we showed that pS81 is preferentially localized in the nucleus in both rapid biopsy metastatic CRPC samples and PCa xenografts, and nuclear pS81 localization is correlated with AR transactivation in tumor xenografts." (PMID 33932081, 2021). "More importantly, SREBP is a key factor in the regulating of tumor growth and distant metastasis in PCa, which can be regulated by AR." (PMID 34822423, 2021). "In vitro studies on PC cell lines have shown that tumor cells with IL-6 increase androgen receptor (AR) expression and function on these cells, affecting many convenient cellular processes." (PMID 34868907, 2021). "Herein, AR mRNA expression was significantly higher in tumor tissues from patients classified as Luminal A, Luminal B, and HER2-enriched compared to tissues from TNBC cases (p < 0.001)." (PMID 34571711, 2021). "It seems that the tumor at this stage still relies on AR signaling, which is adaptively activated via multiple mechanisms." (PMID 34681745, 2021). "We also found that terbinafine reduced the abundance of tumour cells with nuclear AR, suggesting that inhibition of SQLE interferes with AR signalling also in vivo." (PMID 34417456, 2021). "Here, we explored the anti-tumour efficacy of the AR targeted inhibitor enzalutamide combined with cabazitaxel." (PMID 34749299, 2021). "Mechanistically, it seems that the tumor becomes more aggressive through adaptive responses, relies more on alternative activated pathways, and is less dependent on AR signaling." (PMID 34681745, 2021). "Correspondingly, in preclinical mouse model studies, the anti-tumor activity of the AR inhibitor was more marked in female mice harboring GC cells." (PMID 33947843, 2021).
tumor (continued). "AR is known to control tumor growth in ER positive tumors and stimulate disease progression in the absence of ER." (PMID 34234742, 2021). "Our analysis of regulons revealed potential druggable pathways related to sex hormones in distinct tumor subsets: the androgen receptor pathway was significantly activated in class 3 tumors, although there was no enrichment for male patients in this group." (PMID 33863885, 2021). "The implication of androgenic activity in tumor promotion is surprising; it is widely assumed that AR antagonizes ER function in the normal breast." (PMID 34042278, 2021). "AR amplification was also detected in circulating tumor cells (CTCs) from patients with metastatic PCa." (PMID 34067217, 2021). "While ER/AR are known to stimulate cell growth and survival by modulating gene transcription, emerging findings indicate that their effects in neoplasia are also mediated by dysregulation of protein synthesis (i.e., mRNA translation)." (PMID 34209750, 2021). "A promoter methylation signature classifies PC bone metastases into two groups and predicts tumor AR activity and patient prognosis after ADT." (PMID 34193246, 2021). "Ninety-seven percent male and 87.5% female patients, respectively, were found to be positively stained for AR in >1% of tumor cell nuclei (P = 0.33)." (PMID 34094902, 2021). "In preclinical models with PTEN loss, AR and PI3K/AKT pathways maintained tumor survival by reciprocal feedback leading to enzalutamide and abiraterone resistance." (PMID 34771580, 2021). "Genomic sequencing confirmed the authenticity of the fusion events at chromosomal level, suggesting a potential role of AR in promoting tumor translocations." (PMID 33634124, 2021). "HSD3B2 plays a crucial role in steroid hormone biosynthesis and it is up-regulated in a relevant fraction of PCa that are characterized by an adverse tumour phenotype, increased androgen receptor signalling and early biochemical recurrence." (PMID 33509203, 2021). "Androgen receptor (AR) and tumour-infiltrating lymphocytes (TILs) had a prognostic and predictive value in TNBC." (PMID 35047068, 2021). "Both AR mRNA and protein in circulating tumor cells was investigated and shown to be evaluable in blood samples." (PMID 34736512, 2021). "Although enzalutamide treatment by itself was ineffective in reducing tumour growth, it significantly suppressed AR signalling in PC346C-DCC-K tumours as shown by AR target gene expression." (PMID 34749299, 2021). "Several AR variants (ARVs) result from alternative splicing of premature AR and are the real drive behind tumor progression." (PMID 33499881, 2021). "It was postulated that AR acts in an antiproliferative manner in ER-positive tumors by antagonizing ER, whereas it facilitates tumor cell growth in ER-negative tumors in an androgen-dependent manner." (PMID 33915941, 2021). "Among the deregulated molecular events occurring in PCa, AR signaling is historically considered the main carcinogenesis driver, playing a pivotal role both in tumor growth and development of castration-resistant disease." (PMID 34069147, 2021). "We performed correlation studies with the metabolic gene set and AR signature in 8 different PCa transcriptomics datasets containing primary tumor specimens." (PMID 34503116, 2021). "Twenty CAD tumours were studied with immunohistochemistry, in situ fluorescence hybridization and DNA methylation analysis, to evaluate AR expression and its regulator status." (PMID 33534004, 2021). "IHC staining intensity of Ki-67, a marker reflected the proliferation rate of tumor cells, and AR were both significantly weaker in combination treatment group than in the single treatment group or the control group." (PMID 34041015, 2021). "p300 directly acetylates AR or binds to AR, enhancing its transcriptional activity, inducing the expression of oncogenes, and promoting tumor growth." (PMID 34830196, 2021).
tumor (continued). "In summary, our data demonstrated tumor suppressive effects of AR antagonists, particularly enzalutamide, in GBM cell lines and, for the first time, in an orthotopic mouse model." (PMID 34094902, 2021). "The role of AR and its downstream regulatory genes in the transition of the tumor to androgen-independence remains an area of intense interest in the field of PCa research." (PMID 34833084, 2021). "Seventy-nine percent male and 66.7% female patients showed positive AR staining in >10% tumor cell nuclei (P = 0.30)." (PMID 34094902, 2021). "Recent studies have shown that miR-299-3p has the promising capacity to specifically target AR and regress tumor growth in mCRPC." (PMID 34899292, 2021). "In our study, median CD20 was significantly higher in AR− tumours compared to those with AR+ (20% versus 7.5%, respectively, p = 0.008)." (PMID 35047068, 2021). "Though generally highly concordant, in several tumors the assessments of AR, NE, and cell cycle activity from different ROIs within the same tumor also diverged." (PMID 33658518, 2021). "These patient samples also exhibited high tumor:normal AR enrichment at the widely studied AREs near KLK2 and KLK3 suggesting higher overall AR binding." (PMID 34409300, 2021). "Consistently, the in vivo mice model confirmed that knocking down lnc-OPHN1-5 expression in tumors significantly increased the tumor formation rate and AR protein expression compared with the control group." (PMID 34545067, 2021). "During treatment, we also collected blood for serum PSA measurements as a reflection of AR activity and tumor burden." (PMID 33671134, 2021). "Consistently, genetic EP300 ablation attenuates AR expression and inhibits tumor formation in a mouse model of PTEN deletion-induced tumorigenesis in vivo." (PMID 34201346, 2021). "It has been well established that, in contrast to what has been observed in ER-/HER2+/AR+ tumors, HER2+ BC cases expressing high ER and AR levels have smaller tumor sizes, lower Ki-67 percentages, less aggressive phenotypes, and better outcomes." (PMID 34571711, 2021). "Collectively, these results support a role for KLF5 in opposing AR to promote features of basal cell identity, which precedes the emergence of neuroendocrine hallmarks and castration-resistant tumor growth in a model of NEPC progression." (PMID 34737261, 2021). "Collectively, these alterations to AR/ER signalling confer insensitivity to conventional hormone deprivation therapies and highlight the dependency of tumours on these pathways." (PMID 34209750, 2021). "We also studied the expression pattern of AR in GBM tumor specimens from patients treated at our medical center." (PMID 34094902, 2021). "The incidence of AR mutations was estimated to be around 15% for CRPC patients and the availability of circulating tumour DNA assays now provide a sensitive method to serially detect (and treat) the emergence of resistant AR mutants." (PMID 34208290, 2021). "Conversely, we assessed the consequence of ERG overexpression in LNCaP cells under low DHT levels where mutant SPOP triggers AR signaling and tumor growth 19,23." (PMID 33531470, 2021). "These tumours demonstrate a gene expression signature resembling that of endocrine-responsive tumours, are characterised by both AR expression and androgen-dependant growth, and are classically less responsive to conventional cytotoxic chemotherapy." (PMID 34638457, 2021). "Unfortunately, the overall survival benefits of these newer ARPIs in men with CRPC are in the order of months, despite many tumours retaining dependence on AR." (PMID 34382934, 2021). "Even though PC is strongly driven by the AR, many other mechanisms facilitate tumor cell proliferation and enhance metastatic potential, especially in metastatic castration-resistant PC." (PMID 34208621, 2021). "Conversely, blockade of the AR pathway by anti-androgens appears to suppress tumor growth, migration, invasion, and induces apoptosis." (PMID 34063736, 2021).
tumor (continued). "Increasingly more researchers are trying to classify CRPC on the basis of histological phenotypes or by exploring the variation of AR expression, also known as AR heterogeneity in tumor cells." (PMID 35008817, 2021). "Of the five patients with T878 or H875 mutations in AR, two (40%) had a PSA reduction of more than 50%, including one with PR confirmed by RECIST and tumor size reduction of 80%." (PMID 34025443, 2021). "Detection of serum biomarkers of neuroendocrine differentiation and circulating tumor cells is a prospective non-invasive method of detecting neuroendocrine transdifferentiation in patients undergoing treatment with androgen receptor pathway inhibitors." (PMID 33754118, 2021). "AR occupancy at the intron 5 site was particularly strong in 4/6 tumors and was higher than any matched normal peak, suggesting tumor-specific binding of AR to this site." (PMID 34409300, 2021). "After screening and eligibility assessment, a total of 62 datasets reporting AR mRNA expression levels in tumor specimens resected from BC patients were included." (PMID 34571711, 2021). "In the analysis based on tumor stage, our cohort revealed a higher expression of AR in pT1 tissues than in pT4 tissues of ccRCC patients." (PMID 34440475, 2021). "ASC-J9 has shown to reduce cell proliferation and invasion by enhancing AR protein degradation via ubiquitination, leading to suppression of tumour growth both in vitro and in vivo[98." (PMID 33993099, 2021). "In the future, we will further verify the effect of proxalutamide on the endogenous lipid metabolism of PCa tumors in tumor-bearing mouse models, and the correlation between this effect and its effect on the AR signaling pathway." (PMID 34948018, 2021). "Comparative analysis indicated that positive status of ER (37 vs. 63%, p < 0.001), PR (38 vs. 62%, p < 0.001), AR (14 vs. 86%, p < 0.001) expression and peri-tumor nerve invasion (10 vs. 89%, p = 0.009) were correlated with lower TILs." (PMID 34901155, 2021). "The AR is a nuclear hormone receptor that acts as a transcription factor upon activation driving the oncogenic gene expression programme to support tumour progression." (PMID 33993099, 2021). "AR antagonist, bicalutamide, exerted anti-tumor activities and induced apoptosis both in vitro and in vivo, using GC cell lines and female patient-derived xenograft (PDX) model." (PMID 33947843, 2021). "Despite low circulating androgens in the CRPC patients, one potential mechanism that would allow tumor cell proliferation is by promoting the expression of the AR itself, which increases ligand-occupied receptor content." (PMID 34630112, 2021). "Previous studies have shown that multiple pre-treatments will lead to tumor resistance to targeted AR therapy, and improve the heterogeneity of tumor, resulting in a decreased efficacy of AR targeted therapy." (PMID 34025443, 2021). "The tumor strongly relies on systemic/circulating androgens for activating AR signaling to stimulate growth and progression." (PMID 34681745, 2021). "Accordingly, the authors proved that HOTAIR and AR were involved in tumor angiogenesis and cancer stemness maintenance in vitro and in vivo via the Hedgehog-GLI2 signaling pathway." (PMID 34572815, 2021). "These cell-subline models represent different clinical resistance stages during tumor progression and are characterized by blocked or decreased AR and elevated GR levels." (PMID 33795839, 2021).
tumor (continued). "Combined, these findings identify CRY1 as a tumor specific, AR-induced effector of poor outcome in PCa and identify entirely new functions of CRY1 to temporally control HR and the response to genomic insult." (PMID 33452241, 2021). "Because we have focused on the tumor-suppressive function of AR, NKX3.1, a transcriptional repressor (Combined Score: 0.981) was identified." (PMID 34743733, 2021). "The PC pathophysiology includes androgen-receptor signaling aberrations, deleterious somatic and germline abnormalities, irregularities of tumor suppressor and oncogenic genes, and genetic alterations." (PMID 34452154, 2021). "Previous reports concerning AR signaling in the context of in vivo DEN carcinogenesis investigated the role of AR signaling when neoplasia is established." (PMID 33574348, 2021). "Combinatorial therapy targeting MAPK pathway and AR was shown to reduce tumor cell viability and tumor burden." (PMID 34638264, 2021). "In most of the studied tumours, the AR gene was monosomic and its regulators showed a variable methylation status, with a prevalence of hypomethylation." (PMID 33534004, 2021). "Despite its initial effect, hormone therapy eventually fails and the tumor progresses to lethal stages even through continued inhibition of AR." (PMID 33842835, 2021). "At present, the development of anti‐tumour drugs is mainly focused on inhibiting major tumour‐related genes, such as AR and Akt." (PMID 33377281, 2021). "A novel liquid biopsy technology was used to collect mRNA from circulating tumor cells (CTCs) to measure expression of AR-Vs, AR targets, and neuroendocrine prostate cancer markers." (PMID 34197212, 2021). "In line with the results from the cell culture experiments, SIM2 silencing similarly to AR depletion decreased tumor size of VCaP cells in CAM assays, which further points to the importance of SIM2 in the regulation of CRPC cells." (PMID 34127815, 2021). "Accordingly, blocking AR activity and synthesis reduces tumour growth in patient-derived xenograft models." (PMID 35008851, 2021). "AR knockout also reduced the proportion of classical monocytes, which are thought to enter tumor and inflammatory sites and develop into macrophages or dendritic cells." (PMID 34768683, 2021). "Our work proposing that KLF4 can impair AR adds another layer of complexity to KLF4 tumor suppressive function in controlling prostatic cell proliferation and survival." (PMID 33640491, 2021). "In contrast, FGF activates MAPK signaling and bypasses the AR in promoting CRPC tumor growth by inducing the expression of inhibitor of differentiation 1 (ID1)." (PMID 35008817, 2021). "Rakha’s team observed that tumor size, lymph node stage, and androgen receptor are clinical prognostic markers in TNBC." (PMID 35155184, 2021). "Overall, RNA-sequencing confirmed that enzalutamide treatment repressed AR signalling in PC346C-DCC-K tumours." (PMID 34749299, 2021). "Taken together, these data suggest that AR re-expression in AR-negative cell lines induces tumor-suppressive properties by negatively modulating cellular proliferation, migration, and invasion in a DHT-dependent manner." (PMID 33420371, 2021). "The androgen receptor (AR) has been generally regarded as the most integral factor for regulating the development and spread of tumor cells, and consequently, the majority of treatment regimens are directed against the AR pathway." (PMID 33805919, 2021). "Analysis of the relapsed tumor by hematoxylin and eosin staining and immunohistochemistry (IHC) for AR and Ki67 revealed some notable features (treated versus untreated)." (PMID 34575033, 2021). "However, high AR expression is associated with prolonged relapse-free survival, lower grade, and lower number of affected lymph nodes in ERα(+)/PgR(−) BC, thus the mechanistic role of AR and its influence on ERα(+)/PgR(−) tumor aggressiveness requires further studies." (PMID 34638241, 2021).